S1PR1 (sphingosine-1-phosphate receptor 1)
Diseases named in the same sentence as S1PR1 in open-access papers (continued):
Sharing a sentence is not in itself a finding about the gene and the disease.
atherosclerosis (16 papers, 2017 to 2024). A disease characterized by the build-up of fatty material and calcium deposition in the arterial wall resulting in partial or complete occlusion of the arterial lumen. "Administration of KRP-203, a S1PR1 agonist, reduced the development of atherosclerosis in LDL receptor-deficient mice on a cholesterol-rich diet by modulating the lymphocyte and macrophage function and improving the endothelial barrier." (PMID 36119733, 2022). "The role of S1PR1 in atherosclerosis can be demonstrated that in vivo, myeloid‐specific S1PR1 deficiency begat accelerated development of atherosclerosis as well as necrotic core formation and the appearance of apoptotic cells within atherosclerotic plaques." (PMID 32803879, 2020). "Endothelium cell–specific S1PR1 deficiency increases mouse atherosclerosis." (PMID 39343001, 2024). "Similarly, S1P by activating S1PR3 can also promote the development of atherosclerosis, as does S1PR1 by activating endothelial ICAM-1 and VCAM-1 and causing its dysfunction." (PMID 36119733, 2022). "Conditional inactivation of S1pr1 gene expression either in myeloid or endothelial cells increases atherosclerosis in mice." (PMID 38583587, 2024). "While S1pr1-LysMCre mice showed a dramatic reduction of atherosclerosis combined with marked blood count alterations, the respective effects were moderate in S1pr1-F4/80Cre mice." (PMID 39531328, 2024). "Selective inactivation of S1pr1 in BM-derived myeloid cells accelerated the diet-induced development of atherosclerosis and necrotic cores within atherosclerotic plaques." (PMID 29244772, 2017). "Hla and co-workers reported that selective endothelial cell specific S1pr1 KO induced in juvenile ApoE KO mice resulted in enhanced HF diet-induced atherosclerosis." (PMID 29244772, 2017). "We then initiated atherosclerosis development in these mice and control mice with normal S1pr1 expression in BM derived cells by feeding them a HF diet." (PMID 29244772, 2017). "In chronic inflammatory processes such as atherosclerosis, S1P binding to S1PR1 activates the signaling pathway NF-kB, which is responsible for angiogenesis and secretion of proinflammatory cytokines, such as tumor necrosis factor alpha and interleukin 1 beta, from lymphatic endothelial cells." (PMID 36835432, 2023). "Interestingly, the role of S1P and its receptors such as S1PR1 in the development of atherosclerosis is multifaceted." (PMID 37608809, 2023). "Furthermore, the descending aorta of S1pr1 ECKO mice displayed exacerbated plaque formation in the Apoe-/-Western diet (WD)-induced atherosclerosis model." (PMID 32091396, 2020). "While S1pr1 ECKO animals exhibit exacerbated atherosclerosis, we cannot discern whether this was due to phenotypes of lymphatic ECs, arterial ECs, or both cell types." (PMID 32091396, 2020). "Rapamycin may also stabilize artery plaques by preventing apoptosis and S1PR1 in advanced atherosclerosis." (PMID 30627532, 2018).
atherosclerosis (continued). "Finally, selective endothelial cell-specific inactivation of the S1pr1 gene in juvenile mice has been reported to increase atherosclerosis development in response to high fat (HF) diet feeding." (PMID 29244772, 2017). "To test if SR-B1 and S1PR1 form complexes in cells within atherosclerotic plaques, we generated S1pr1eGFP/eGFP/ApoEKO/KO mice and fed them a high fat, high cholesterol, atherogenic diet for 8 weeks to promote atherosclerosis development in their aortic sinuses." (PMID 38583587, 2024). "Similarly, S1PR1 inactivation in endothelial cells also increased atherosclerosis." (PMID 38583587, 2024). "Hence, rapamycin-induced autophagy in foam cells delays intracellular lipid accumulation and may stabilize artery plaques through prevention of apoptosis and S1PR1 in advanced atherosclerosis." (PMID 30627532, 2018). "Mice with atherosclerosis that are treated with FTY720, a competitor of S1P, have fewer lymphatic vessels, which implies that S1P/S1PR1 is a pathway involved in vessel tube formation." (PMID 36835432, 2023). "With respect to atherosclerosis, little evidence could be found supporting the attenuating effect of S1P1 signaling in neutrophils on vascular lesion development in myeloid S1pr1-deficient mice." (PMID 39531328, 2024). "Additionally, the finding that FTY20 inhibited S1PR3 and S1PR4 in macrophage foam cells was similar to previous reports that FTY20 could suppress S1PR1 and S1PR3 to decrease inflammatory factors and alleviate atherosclerosis." (PMID 30627532, 2018). "The role of macrophage S1PR1 in atherosclerosis, however, has not been described." (PMID 29244772, 2017). "For example, 11C-TZ3321 can detect the up-regulation of S1PR1 in inflammatory blood vessels, and the expression of S1PR1 is higher in neointimal hyperplasia, so 11C-TZ3321 may realize the detection of early inflammation or can be used in the diagnosis and prognosis of atherosclerosis." (PMID 34484174, 2021).
Obesity (16 papers, 2018 to 2025). Accumulation of substantial excess body fat. "Targeting the SphK1/S1P/S1PR1 axis with specific drugs can reduce tumor progression caused by key proinflammatory cytokines, macrophage infiltration, and obesity." (PMID 33747044, 2021). "All the data indicated that the S1P/S1PR1/S1PR3-YAP signaling could be an underlying mechanism contributing to aggressive behavior of tumor growth in obesity-lymphoma." (PMID 36600310, 2023). "As such, the SK1/S1P/S1PR1 axis is potentially implicated in obesity-related inflammation." (PMID 32266132, 2020). "Targeting the SphK1/S1P/S1PR1 axis mediated by lipid metabolism attenuates key pro-inflammatory cytokines and macrophage infiltration as well as obesity-induced tumor progression." (PMID 36880535, 2023). "The expression of obesity-related mediators (SphK1 and S1PR1) is enhanced in metastatic lesions of syngeneic and spontaneous breast tumor obese mice, along with elevated levels of TNF-α and IL-6." (PMID 36880535, 2023). "Obesity‐related inflammation increases the expression of S1P, acts on S1PR1, promotes macrophage infiltration and tumor progression, and confirms the role of circulating S1P produced by tumor and SphK1/S1P/S1PR1 axis in inflammation and tumor metastasis." (PMID 37902101, 2023). "Obesity enhances the expression of sphingosine kinase 1 (SphK1), the enzyme that produces S1P and its receptor S1PR1." (PMID 36670988, 2023). "FTY720 was also shown to inhibit obesity-related inflammation, proliferation, and metastasis by inhibiting S1PR1." (PMID 33758708, 2021). "It was shown to reduce S1P levels and SK1 and S1PR1 expression in the breast tumors, as well as reduce key proinflammatory cytokines, macrophage infiltration, and tumor progression induced by obesity." (PMID 32266132, 2020). "Indeed, obesity-induced breast tumors increase SphK1 and secrete S1P, which promotes macrophage recruitment through S1PR1 in lung premetastatic niches." (PMID 36670988, 2023). "The S1P/S1PR1/ceramide axis can activate the hunger signaling pathway in the hypothalamus through S1P so as to increase energy consumption and lipolysis, reduce food intake, thereby producing anti-obesity effects." (PMID 35966072, 2022).
bladder cancer (15 papers, 2018 to 2025). "In this study, we analyze the association between S1PR1 expression and patient prognosis by exploring several bladder cancer clinical databases." (PMID 34503284, 2021). "Using comparative analysis of bladder cancer cell lines and clinical tissues, we confirmed the association of S1PR1 with cell adhesion ability in bladder cancer cells." (PMID 34503284, 2021). "In cancer progression, S1PR1 is thought to be highly expressed in bladder cancer cells and is associated with poor patient prognosis." (PMID 34503284, 2021). "Several publications have demonstrated the association of S1PR1 overexpression with worse prognosis in bladder cancer patients." (PMID 34503284, 2021). "To comprehensively evaluate the association between S1PR1 expression and prognosis of bladder cancer patients, we collected six available databases including GSE5287, GSE13507, GSE31684, GSE32894, GSE48075, and TCGA BLCA." (PMID 34503284, 2021). "The meta-analysis showed that the overall odds ratio still reached 1.681, indicating that, in general, high S1PR1 expression was associated with a worse prognosis in bladder cancer." (PMID 34503284, 2021). "Comparative analysis of clinical tumor tissues with bladder cancer cells suggests that S1PR1 expression is associated with cellular adhesion." (PMID 34503284, 2021). "The effect of S1PR1 itself on cancer cells was associated with cell adhesion, and in bladder cancer cells, S1PR1 expression was negatively correlated with cell motility." (PMID 34503284, 2021). "This article first revealed that loss of S1PR1 expression in bladder cancer cells is associated with increased cell motility and that inhibition of S1PR1 activity with FTY-720 may cause a similar phenomenon." (PMID 34503284, 2021). "However, our study clearly indicates that reduction of S1PR1 expression by human manipulation may cause a promotion in EMT in bladder cancer cells and patient tumor tissue, a phenomenon consistent with FTY-720 treatment." (PMID 34503284, 2021). "Moreover, a similar phenomenon could be observed in the patient-derived tumor primary culture model, suggesting that clinical inhibition of S1PR1 may cause accelerated metastasis of bladder cancer cells." (PMID 34503284, 2021). "Several studies found an elevated expression of S1PR1 in bladder cancer, especially in high-grade tumors." (PMID 39595959, 2024). "as it was reported that the expression of S1P receptors, S1PR1, S1PR2 and S1PR3 is linked to the pathological grades and stages of bladder cancer." (PMID 39315290, 2024). "On the contrary, we observed that angiogenesis and cell adhesion gene clusters were positively associated with S1PR1 expression in all three, suggesting that the real effect of S1PR1 on bladder cancer is related to these gene clusters." (PMID 34503284, 2021). "The results showed that S1PR1 expression was generally higher in normal tissues than in bladder cancer tissues, and its distribution was mainly in endothelial cells or immune cells." (PMID 34503284, 2021). "S1PR1 stimulates bladder cancer cells to secrete transforming growth factor (TGF)-β and IL-6, thereby inducing the aggregation of regulatory T-cells (Tregs)." (PMID 34484174, 2021). "Correlation of S1PR1 with pathological grade in tumors suggests its potential as a prognostic tool for patients with bladder cancer as well as liver and gallbladder cancers." (PMID 34503284, 2021). "Only the J82 bladder cancer cell line has a near normal copy number and moderate mRNA expression of the S1PR1 gene." (PMID 34503284, 2021). "Myeloid cells or murine bladder cancer cells with elevated expression of S1PR1 (one of the receptors for S1P) produced more IL6." (PMID 34638448, 2021). "In conclusion, high expression of ADRA2A, CXCL12, S1PR1, ADAMTS9, F13A1, and SPON1 was associated with poor overall survival in bladder cancer patients, with a P-value <0.05 considered to be statistically significant." (PMID 32239176, 2020).
bladder cancer (continued). "Inhibition of S1PR1 enhanced cancer cell migration in bladder carcinoma." (PMID 40057751, 2025). "Furthermore, in the context of bladder cancer, S1PR1 exhibits inhibitory effects on cell migration by suppressing epithelial-mesenchymal transition (EMT)." (PMID 39551792, 2024). "Conversely, the use of FTY720 as an S1PR1 antagonist promotes EMT in bladder cancer cells." (PMID 39551792, 2024). "Further studies have indicated elevated expression of S1PR1 in bladder cancer tissue." (PMID 34484174, 2021). "As our analysis shows that S1PR1 expression is associated with angiogenesis, it is possible that bladder cancer cells overexpressing S1PR1 may affect tumor progression by altering microenvironmental angiogenesis." (PMID 34503284, 2021). "As S1PR1 is important for the regulation of immune cell movement, we wondered whether it might have a similar role in the metastasis of bladder cancer cells." (PMID 34503284, 2021). "Therefore, to avoid potential interference with genetic abnormalities, the J82 bladder cancer cell line was used to establish a stable expression of S1PR1 targeting shRNA clone." (PMID 34503284, 2021). "S1PR1 expression promotes cancer cell adhesion and, conversely, inhibition of S1PR1 by genetic manipulation or FTY-720 may increase bladder cancer cell migration ability." (PMID 34503284, 2021). "This suggests that the enriched neutrophil infiltration may directly affect the prognosis prediction of bladder cancer patients using S1PR1 expression." (PMID 34503284, 2021). "There are many factors in clinical bulk tissue that may affect S1PR1 expression, such as the infiltration of endothelial or immune cells, which may lead to misinterpretation of the biological response of S1PR1 expression in bladder cancer cells." (PMID 34503284, 2021). "A negative correlation between S1PR1 expression and cell motility was also confirmed in bladder cancer cell lines." (PMID 34503284, 2021). "FTY-720 is identified to inhibit cell proliferation and promote apoptosis by regulating S1PR1; however, the effect of FTY-720 on EMT in bladder cancer remains unknown." (PMID 34503284, 2021).
Cerebral ischemia (15 papers, 2015 to 2023). Restriction of arterial blood supply to the brain associated with insufficient oxygenation to support the metabolic requirements of the tissue. "S1P receptors, S1PR1 is amongst the most abundant subtype of S1P receptors in the brain, which plays a crucial role in sustaining hallmark endothelial functions and could be as a regulator for microglial activation following cerebral ischemia." (PMID 34026822, 2021). "This work also revealed a critical protective role for cerebrovascular autonomous engagement of S1PR1 during cerebral ischemia and that this receptor pool is a potential target for neuroprotection with blood–brain barrier (BBB)-penetrating S1PR1 agonists." (PMID 37142226, 2023). "Inhibition of S1PR1 activity with AUY954 not only alleviated the pro-inflammatory response but also enhanced the anti-inflammatory response after cerebral ischemia." (PMID 35242008, 2022). "The pathogenicity of S1PR1 in cerebral ischemia is related to neuroinflammation." (PMID 35242008, 2022). "Conversely, increased expression of S1PR1, whose activation has been reported to be beneficial in experimental models of cerebral ischemia, could eventually represent a protective factor in SHRSR." (PMID 33917593, 2021). "Furthermore, MEK/Erk pathway has been reported to play protective roles for neurons survival in DG and also contribute to the antiapoptotic effect of S1PR1 on neurons in injured cortex after cerebral ischemia." (PMID 28018679, 2016). "In addition, the regulatory role of S1PR1 in proinflammatory response after cerebral ischemia may be related to the activation of microglia." (PMID 35242008, 2022). "S1PR1 modulators involved in S1P1 signaling pathway improve microvascular circulation after thrombosis and exert beneficial roles in cerebral ischemia." (PMID 32194396, 2020). "A previous study revealed that the neuroprotective effects of SEW2871 and the non-selective S1PR1 agonist FTY720 against cerebral ischemia in a mouse stroke model occurred by means of apoptosis prevention and a reduction in infiltration by immune cells." (PMID 26367258, 2015).
glioma (15 papers, 2006 to 2025). A benign or malignant brain and spinal cord tumor that arises from glial cells (astrocytes, oligodendrocytes, ependymal cells). "S1P stimulates cell proliferation of glioma cells by activating the S1PR1 and S1PR3 receptors that promote ERK signaling." (PMID 39698539, 2024). "The consequent SK1/S1PR1 signaling stimulates glioma proliferation and survival via AKT, cMYC, and STAT3 pathways." (PMID 39698539, 2024). "Then, VPC 23019, a S1PR1 and S1PR3 antagonist, was used to verify the roles of S1PRs on the anti-glioma effects of FTY720." (PMID 32194542, 2020). "Also upregulated is S1PR1 (sphingosine-1-phosphate receptor 1, also described as S1P1), increased levels of which are known to avert T cell sequestration and license immunotherapeutic responses to glioma." (PMID 40244705, 2025). "Notably, only S1PR1 and S1PR2 were expressed on C6 glioma cells, which is not consistent with the reported expression in glioma patient samples." (PMID 32977496, 2020).